OR5H2 (olfactory receptor family 5 subfamily H member 2)
Description:
Odorant receptor.
Synonyms: OR3-10
Tractability: Antibody: UniProt places it where antibodies can reach, with medium confidence; UniProt predicts a signal peptide or a membrane-spanning region; its Gene Ontology location is reachable by antibodies, with medium confidence.
Gene: Protein-coding gene on chromosome 3 (98,282,505 to 98,284,070, forward strand). Ensembl gene ENSG00000197938.
Subcellular location: Cell membrane
Pathways (Reactome):
Sensory Perception: Expression and translocation of olfactory receptors
Gene Ontology:
Molecular function: odorant binding; olfactory receptor activity; G protein-coupled receptor activity
Biological process: sensory perception of smell; detection of chemical stimulus involved in sensory perception of smell; G protein-coupled receptor signaling pathway
Cellular component: plasma membrane; membrane
Genetic constraint (gnomAD): Missense variants: 355 observed, 348.49 expected, observed/expected ratio (o/e) 1.02, 90% interval 0.93 to 1.11. Synonymous variants: 122 observed, 122.93 expected, observed/expected ratio (o/e) 0.99, 90% interval 0.86 to 1.15.
Homologues: Orthologues: macaque OR5H2 (95% identical), dog OR5H13 (79% identical), dog OR5H11 (78% identical), dog OR5H9 (78% identical), rat Or5h18 (78% identical), mouse Or5h18 (77% identical), dog OR5H12 (77% identical), dog OR5H16 (77% identical), rat Or5h17 (76% identical), mouse Or5h25 (76% identical), mouse Or5h17 (75% identical), mouse Or5h26 (75% identical), and 13 more. Paralogues in human: OR5H1 (80% identical), OR5H14 (79% identical), OR5H15 (79% identical), OR5H6 (78% identical), OR5H8 (67% identical), OR5AC2 (64% identical), OR5K4 (55% identical), OR5K1 (54% identical), OR5K2 (51% identical), OR5K3 (51% identical), OR8U1 (51% identical), OR5B12 (51% identical), and 84 more.
Diseases named in the same sentence as OR5H2 in open-access papers:
OR5H2 is named in the same sentence as 4 diseases in open-access papers, as found by Europe PMC text mining. Sharing a sentence is not in itself a finding about the gene and the disease. The quoted sentences say what the papers report.
endometrial cancer (3 papers, 2021 to 2025). Primary or metastatic malignant neoplasm involving the endometrium (mucous membrane that lines the endometrial cavity). "Of interest, OR5H2 knockdown in both endometrial cancer cell lines led to marked reductions in IGF1R protein levels and in the total and phosphorylated levels of the AKT and ERK1/2 cytoplasmic mediators." (PMID 34204736, 2021). "Our data demonstrate that the OR5H2 gene constitutes a novel target for IGF1 action in endometrial cancer." (PMID 34204736, 2021). "To investigate the potential role of the OR5H2 gene in endometrial cancer biology, we measured the basal OR5H2 mRNA levels in the USPC1 and USPC2 cell lines in the initial experiments." (PMID 34204736, 2021). "The aim of our study was to investigate the regulation of OR5H2 gene expression by IGF1 in endometrial cancer." (PMID 34204736, 2021). "OR5H2 could regulate endometrial cancer cell proliferation by interacting with the IGF1 signaling pathway, and OR5B21 drove breast cancer metastasis." (PMID 40523880, 2025). "Next, we investigated the effect of OR5H2 expression on endometrial cancer cell proliferation." (PMID 34204736, 2021). "OR5H2 emerged as a new target for positive regulation by IGF1, with potential relevance in endometrial cancer biology." (PMID 34204736, 2021). "In summary, OR5H2 emerged as a novel target for positive regulation by IGF1, with potential relevance in endometrial cancer." (PMID 34204736, 2021). "The identification of OR5H2 as an IGF1-dependent, mitogenic factor in endometrial cancer might help in these efforts." (PMID 34204736, 2021).
cancer (1 paper, 2021). A tumor composed of atypical neoplastic, often pleomorphic cells that invade other tissues. "The fact that OR5H2 is under-represented in LS, a genetic condition associated with cancer protection, provides further support to the concept that OR5H2 has an important role in the biology of cancer." (PMID 34204736, 2021).
OR5H2 also shares sentences with these, for which no sentence is quoted: breast carcinoma (1 paper); tumour (1).